HBA2 (hemoglobin subunit alpha 2)
Description:
Involved in oxygen transport from the lung to the various peripheral tissues. [Hemopressin]: Hemopressin acts as an antagonist peptide of the cannabinoid receptor CNR1. Hemopressin-binding efficiently blocks cannabinoid receptor CNR1 and subsequent signaling.
Synonyms: HBA-T2; ECYT7; HBH
Tractability: Small molecule: an approved drug acts on it; a structure with a bound ligand is known; a high-quality ligand is known; it has a high-quality binding pocket. Antibody: its Gene Ontology location is reachable by antibodies, with high confidence. PROTAC: ubiquitination databases record sites on it.
Target class: Secreted protein
Safety:
Unwanted effects reported when the protein is acted on. In parentheses: how it was acted on, where the effect was seen, and who reports it.
N/A, Cyanosis occurs (source: AOP-Wiki)
Gene: Protein-coding gene on chromosome 16 (172,876 to 173,710, forward strand). Ensembl gene ENSG00000188536.
Pathways (Reactome):
Cellular responses to stimuli: Cytoprotection by HMOX1; Heme signaling
Transport of small molecules: Erythrocytes take up carbon dioxide and release oxygen; Erythrocytes take up oxygen and release carbon dioxide
Disease: Heme assimilation
Vesicle-mediated transport: Scavenging of heme from plasma
Gene Ontology:
Molecular function: haptoglobin binding; peroxidase activity; protein binding; heme binding; oxygen carrier activity; iron ion binding; oxygen binding
Biological process: hydrogen peroxide catabolic process; inflammatory response; nitric oxide transport; oxygen transport; response to hydrogen peroxide; carbon dioxide transport; erythrocyte development; cellular oxidant detoxification
Cellular component: blood microparticle; extracellular exosome; extracellular region; haptoglobin-hemoglobin complex; hemoglobin complex; membrane; cytosol; endocytic vesicle lumen
Genetic constraint (gnomAD): Loss-of-function variants: 5 observed, 3.69 expected, observed/expected ratio (o/e) 1.36, 90% interval 0.66 to 1.91. That is too few expected variants to judge how well the gene tolerates losing a copy. Missense variants: 44 observed, 58.22 expected, observed/expected ratio (o/e) 0.76, 90% interval 0.59 to 0.97. Synonymous variants: 16 observed, 30.52 expected, observed/expected ratio (o/e) 0.52, 90% interval 0.35 to 0.8.
Gene-disease validity (ClinGen):
ClinGen rates the evidence that HBA2 causes each of these diseases.
erythrocytosis, familial, 7 (autosomal dominant): Limited.
methemoglobinemia, alpha type (autosomal dominant): Limited.
unstable hemoglobin disease (autosomal dominant): Limited.
Homologues: Orthologues: chimpanzee HBA1 (100% identical), macaque HBA (96% identical), macaque HBA1 (96% identical), mouse Hba-a1 (87% identical), mouse Hba-a2 (87% identical), rat Hba-a3 (79% identical), guinea pig GLNC1 (76% identical), dog HBQ1 (73% identical), rat Hba-a2 (67% identical), rat Hba-a3 (65% identical), tropical clawed frog hba1 (58% identical), zebrafish hbae4 (46% identical), and 3 more. Paralogues in human: HBA1 (100% identical), HBQ1 (62% identical), HBZ (60% identical), HBM (45% identical), HBB (44% identical), HBD (44% identical), HBG1 (42% identical), HBG2 (42% identical), HBE1 (39% identical), CYGB (32% identical), MB (26% identical).
Diseases named in the same sentence as HBA2 in open-access papers:
HBA2 is named in the same sentence as 86 diseases in open-access papers, as found by Europe PMC text mining. Sharing a sentence is not in itself a finding about the gene and the disease. The quoted sentences say what the papers report.
thalassemia (105 papers, 2010 to 2026). An inherited blood disorder characterized by a decreased synthesis of one of the polypeptide chains that form hemoglobin. "Once low levels of MCV (< 80 fL) or MCH (< 27 pg), high or low levels of HbA2, or abnormal Hb variants are detected, we will detect the thalassemia gene using GAP‐PCR and the reverse dot blot hybridization assays." (PMID 41532136, 2026). "For instance, mutations in the HBB and HBA2 genes are linked to thalassemia, while ATP7B mutations cause Wilson’s disease." (PMID 40136557, 2025). "All involved the critical HS-40 regulatory region and both HBA1 and HBA2 structural genes, consistent with α0-thalassemia alleles." (PMID 41009357, 2025). "In thalassemia diagnostics, the Comprehensive Analysis of Thalassemia Alleles (CATSA) framework achieved 100% accuracy for rare variants like the α3.7III subtype by spanning GC-rich HBA1/HBA2 loci." (PMID 41301752, 2025). "It was found that β-thalassemia definitive diagnosis rates were higher in the group diagnosed with other blood diseases and in the group with conditions associated with high HbA2 (p = 0.01)." (PMID 39926651, 2025). "For example, the HBB and HBA2 genes are associated with thalassemia, the ATP7B gene is linked to Wilson’s disease, and a specific set of genes is related to hepatocellular carcinoma." (PMID 40136557, 2025). "A custom-designed liquid phase chip for gene detection associated with thalassemia was then used and confirmed partial deletions of HBA2 (NM_000517) and upstream HBA1 (NM_000558.5) (-α3.7)." (PMID 38982507, 2024). "CD 142 (HBA2:c.427T>C), known as HB Constant Spring, is a labile α-globin variant causing α-thalassemia, due to a common missense mutation of the termination codon of HBA2; Term→Gln." (PMID 37189480, 2023). "Many factors influence HbA2 levels besides the β-thalassemia alleles, such as α-thalassemia, δ-thalassemia and severe IDA26." (PMID 35354866, 2022). "Among the five novel thalassemia mutations, only the hematological parameter of HBA2:c.54delC heterozygous carrier showed hypochromic microcytic." (PMID 34708592, 2021). "We found 55 individuals (32.7%) with α-thalassemia mutations, 51(30.4%) carrying the -α3.7 deletion, one with the -α4.2 deletion and three having the rare punctual mutation HBA2:c.-59C>T." (PMID 33769430, 2021). "We found that 16% of the healthy donors carried pathogenic hemoglobin alleles, including 5 heterozygotes for hemoglobin S (HbAS), 4 heterozygotes for hemoglobin C (HbAC), and 11 individuals with one or two copies of an HBA2 deletion causing α-thalassemia." (PMID 34553687, 2021). "Another frequent cause of a+-thalassemia is the deletion of 4.2Kb (-α4.2 deletion) which deletes the entire HBA2 gene." (PMID 33769430, 2021). "Thalassemias are caused by mutations in the α (HBA1/HBA2) and β globin (HBB) genes and are usually inherited in an autosomal recessive manner." (PMID 33072976, 2019). "Our study population has a high number of different β+- and β0-thalassemia mutations resulting in the heterogeneity of HbA2 levels." (PMID 23577263, 2013). "This study substantiates that HbA2 is lower if iron deficiency or the α-thalassemia trait are present; it is unaffected by gender, smoking, or tribal allegiance." (PMID 23577263, 2013). "Additionally, elevated HbA2 levels associated with SNVs in the β-globin gene cluster are frequently used as an initial screening indicator for α-thalassemia prior to confirmatory genetic testing." (PMID 41229428, 2025). "Previous studies showed that HbA2 and fetal hemoglobin levels were increased and very significantly reduced Hb level in the presence of α‐globin gene triplications in association with β‐thalassemia." (PMID 35844714, 2021). "α‐Thalassemia and β‐thalassemia are two main types of thalassemia, which are caused by variants of HBA1 (OMIM 141800)/HBA2 (OMIM 141850) and HBB (OMIM 141900) genes." (PMID 41532136, 2026).
thalassemia (continued). "The normal value of HbA2 raises the possibility of delta-beta thalassemia (HbS/δβ0-thalassemia), where the HbA2 is low or normal owing to the deletion of the delta-globin gene." (PMID 40084327, 2025). "In this cohort, the prevalence of thalassemia, caused by pathogenic variants in HBA1/HBA2 and HBB, was 1/13, which aligns with previously reported findings." (PMID 40421383, 2025). "Among them, 113 cases had -α3.7/αα, 25 cases had -α4.2/αα, 16 cases had αwsα/αα, 3 cases had --SEA/αα, and 1 case had αcsα/αα which was identified as thalassemia due to the appearance of the cs band during the detection of HbA2 by capillary electrophoresis." (PMID 40758675, 2025). "This region includes HBM, HBA2, HBA1 and HBQ1, which is associated with the pathogenesis of α-thalassemia." (PMID 41444645, 2025). "More than 250 single nucleotide variants (substitutions, microdeletions, or microduplications) relate to α-thalassemia and are more often observed in HBA2 gene than HBA1." (PMID 38542374, 2024). "Globin HBA1/HBA2 testing in this individual confirmed the cis deletion (αα/--) consistent with the α-thalassemia trait." (PMID 39062615, 2024). "Although we excluded HBA1, HBA2, and HBB genes causing thalassemia and hemoglobinopathies, the carrier rate of at least one screened disorder was still as high as 14.7% (241/1642) in our cohort." (PMID 38167091, 2024). "We observed that 23.8% of individuals were carriers of thalassemia and hemoglobinopathies (HBB, HBA1, and HBA2), followed by 7.7% who were carries of G6PD deficiency." (PMID 38167091, 2024). "Laboratory blood data were evaluated (including Hb, MCV, MCH, HbA2, and ferritin levels) and DNA was isolated to confirm the type of thalassemia carrier." (PMID 38716362, 2024). "Beyond that, we identified six rare thalassemia genotypes: HBA2 c.272_279delAGCTTCGG heterozygote, HBB c.180G>C heterozygote, HBB c.341T>A heterozygote, HBB c.68A>C heterozygote, HBB c.68A>G heterozygote, and heterozygous deletion of HBB exons 1-3." (PMID 38660679, 2024). "An unexpected mutation, located in the promoter region of the α2-globin gene, Cap +14(C>G) [HBA2:c.-24C>G], was identified in two patients with HbE-β+-thalassemia with low HbF levels, whose β-globin genotype was βE/βMalay and βE/βDhonburi." (PMID 37816374, 2023). "A recent study identified HbA2 an efficient indicator for detecting intermediate types of thalassemia including α-, β-, and αβ compound thalassemia." (PMID 37580329, 2023). "Cutoff values of HbA2, HbE, and HbF levels for the differentiation of HbE-β+-thalassemia from HbE heterozygotes were determined." (PMID 37816374, 2023). "In the current study, we re-assessed the reference values of HbA2 and HbF in the child-bearing age population in Chongqing, China, and evaluated the levels of HbA2 in thalassemia screening." (PMID 35414613, 2022). "Secondly, the HbA2 reduce group was 6.4% (931/14518) of the total, as there were 14,518 thalassemia screening people were included in this study." (PMID 35971149, 2022). "Based on Hb analysis, we found that there are significant differences between the levels of HbA2 and HbF in β0-thalassemia and β+-thalassemia, where the levels of HbA2 in β0-thalassemia were between 1.7 and 6.6% with a median of 5.1%." (PMID 35573052, 2022). "In the present study, we recruited a thalassemia patient with β41-42 (TCTT) deletions in the human β-globin (HBB) gene and a Hb-WS mutation (ααWS/αα) in the human hemoglobin alpha 2 (HBA2) gene." (PMID 35255977, 2022). "The thalassaemia phenotype group describes the allele phenotype and includes HBA1 and HBA2 variants (α+/α0 and α+; total: 146 SNVs) and HBB variants (β0, β0/β+, β+, β++ (silent) and β++; total: 289 SNVs)." (PMID 36453528, 2022). "A total of 5640 child-bearing age in Chongqing, China, were enrolled in this study to get HbA2 cut-off points for thalassemia prediction." (PMID 35414613, 2022).
thalassemia (continued). "Recent reports have shown the success of genetic correction of an HBB or HBA2 gene in thalassemia-specific hiPSCs using the CRISPR-Cas9 technique." (PMID 35255977, 2022). "The typical haematology characteristics of α-thalassemia patients were up-regulation of HbA and down-regulation of HbA2." (PMID 35971149, 2022). "There was a relationship in the mean/median of hematological parameters, HbA2 and HbF, between β0-thalassemia and β+-thalassemia (P < 0.05)." (PMID 35573052, 2022). "The SMRT method developed in this study focused on detection of variants in HBA1, HBA2, and HBB genes, which consisted the vast majority of thalassemia variants." (PMID 34690349, 2022). "α- and β-Thalassemia are the most common forms of thalassemia, resulting from mutations in the α- and β-globin gene clusters (HBA1, HBA2, and HBB) on chromosome 16 and chromosome 11, respectively." (PMID 35783323, 2022). "We calculated the cutoff point of HbA2 of β0-thalassemia in this study using the ROC curve, finding that HbA2 level ≥ to 4.65% was predicted to be β0-thalassemia, with sensitivity 88% and 74% of specificity." (PMID 35573052, 2022). "Specifically, in α-thalassaemia the genomic deletion in the 3′-end of forward LUC7L gene produces an elongated transcript that overlaps the HBA2 reverse gene." (PMID 34215320, 2021). "CRISPR/Cas9 genome editing to down-regulate α-globin by deleting one of the two α-globin genes (HBA2) to recreate an α-thalassemia trait was reported in a recent in vitro study." (PMID 34713267, 2021). "MCV < 80 or MCH < 27 were used as cut-off values for thalassemia screening, and the normal reference intervals for HbA2 and HbF were 2.5–3.5% and less than 1.0%, respectively, in several studies based on Chinese population." (PMID 32930850, 2020). "The first line of screening for identification of thalassemia carriers is a complete blood count followed by a measurement of HbA2 and HbF proportions." (PMID 31941534, 2020). "One copy of 16p13.3 microdeletion including HBA1 and HBA2 was diagnosed to be a carrier of α thalassemia." (PMID 32842633, 2020). "In a recent report, we showed that HbA2 values were consistent with heterozygous β‐thalassemia in a total of 0.8% of Kilifi Genetic Birth Cohort members with an HPLC pattern suggestive of HbAA." (PMID 32394645, 2020). "This transcript leads to CpG methylation-induced silencing of HBA2 eliciting α-thalassemia phenotype." (PMID 32639509, 2020). "For screening samples with alpha (α-) thalassaemia silent/trait or beta (β-) thalassemia trait, the optimal HbA2 cut-off values were ≤ 2.2% and > 2.8%, respectively." (PMID 28900367, 2017). "In the present study, we found the optimal HbA2 cut-off values for screening samples with α-thalassaemia silent/trait or β-thalassemia trait were ≤ 2.2% and > 2.8%, respectively, which was consistent with the previous report for β-thalassemia." (PMID 28900367, 2017). "α-Thalassemia (α-thal) is a genetic disorder caused by the substitution of single amino acid or large deletions in the HBA1 and/or HBA2 genes." (PMID 26824843, 2016). "Increased HbA2 is valuable for the diagnosis of the common forms of thalassemia whilst HbF along with a low MCH brings out the rarer δβ forms." (PMID 25883737, 2014). "Thirty-five of 158 Hb SS (22.1%) had MCV2% (mean 2.81±1.38) while the remaining 6 had borderline HbA2 (3.5-4.0%) which is suggestive of dβ thalassaemia." (PMID 25400838, 2014). "Hemoglobin electrophoresis and HbA2 levels are often used as part of the laboratory investigations to diagnose thalassemia carriers." (PMID 24385756, 2013). "The results improved, and 80.5% with genetic anemia were detected, 87.9% β-thalassemia carriers, 83.3% α-thalassemia carriers, and 72.1% in the mixed group were correctly classified, so we propose a diagnostic based on MDA and HbA2 analyses." (PMID 24093062, 2013).
thalassemia (continued). "HbA2 was noted to be highest in β-thalassemia trait, and lowest in α-thalassemias (excluding the HbE disorders where HbE and HbA2 fall in the same window and A2 is not detected separately)." (PMID 22084704, 2011). "With the introduction of NGS, retrospective analysis of these samples using the Devyser Thalassemia panel confirmed the MLPA-detected deletions, validating the loss of critical regions including HBA1, HBA2, and HS-40, reinforcing their classification as full α0 deletions." (PMID 41009357, 2025). "Notably, both key genes associated with thalassemia, HBA1 and HBA2, are completely deleted, leading to the manifestation of α0-thalassemia." (PMID 40129608, 2025). "In spite of the fact that HbA2 is still the gold standard and a more reliable test for the diagnosis of thalassemia, gene study plays a very important role in the confirmation of the diagnosis of equivocal cases and the detection of the genetic defect in such cases." (PMID 39463537, 2024). "Although quantifying HbA2 using techniques such as capillary electrophoresis or high-performance liquid chromatography is effective in detecting most β-thalassemia traits, identifying α-thalassemia traits remains challenging owing to limited screening tests." (PMID 38894721, 2024). "Furthermore, the HbA2 level in beta-thalassemia carrier is more than the normal level of 3.5%, but in this study, there were some carrier individuals with normal HbA2 level." (PMID 38322302, 2024). "The most common non-deletion α-thalassemia genotype was HBA2 c.369C>G heterozygous mutation, accounting for 2.38% (2/84) of α-thalassemia cases." (PMID 38660679, 2024). "Additionally, a deletional A at the translation initiation codon of the α2-globin gene (ATG>-TG) [HBA2:c.1delA] was identified in one patient with HbE-β+-thalassemia with a low HbF level, whose β-globin genotype was βE/β−28." (PMID 37816374, 2023). "Above defined variants of HBA2, HBE1 and HBG1 might confer the thalassemia phenotype in the Pakistani population." (PMID 37580329, 2023). "The genes HBA1 and HBA2 of α-thalassemia are located at the end of the p arm of chromosome 16." (PMID 38075678, 2023). "The lower levels found in the current study compared to the threshold used by the guidelines used for the screening of thalassemia in which levels of HbA2 in thalassemia suggestive of β0-heterozygotes were 4–9% and in β+-thalassemia between 2.9 and 6% with a median of 4.3%." (PMID 35573052, 2022). "Long-range PCR and long-molecule sequencing on the PacBio Sequel II platform utilized in this study could cover the entire HBA1, HBA2 and HBB genes, enabling the diagnosis of most of the common and rare types of thalassemia variants." (PMID 35701592, 2022). "The blood routine examination of c.−248A>G carrier was normal, mainly manifested as a decrease in HbA2 content.The phenotype of c.316-45G>C, c.316-179A>C, and c.315+308delA combined with other types of α-thalassemia may be as silent or mild α-thalassemia." (PMID 34690349, 2022). "In addition to the standard GATK pipeline, specific bioinformatics tools have been used to improve the deletion detection of SMN1 and HBA1/HBA2 in spinal muscular atrophy and thalassaemia, respectively." (PMID 35314707, 2022). "A novel strategy was developed by combining 2 therapeutic approaches mediated by CRISPR/Cas9; deletion of HBA2 gene to recreate α-thalassemia trait with reduced α-globin production and integration of β-globin transgene downstream the HBA2 promoter to increase β-globin expression." (PMID 35783328, 2022). "Besides, based on Hb analysis, HbA2 and HbF levels were higher in β0-thalassemia compared to β+-thalassemia with a P value <0.05." (PMID 35573052, 2022). "In addition, we found that HBA1 and HBA2, genes involved in malaria resistance by the sickle cell and thalassemia traits, which also explains the high prevalence and specific pattern of thalassemia in the present-day DAI." (PMID 35864541, 2022).